CCR2 (C-C motif chemokine receptor 2)
Diseases named in the same sentence as CCR2 in open-access papers (continued):
Sharing a sentence is not in itself a finding about the gene and the disease.
tumor (continued). "CCR2-expressing cells migrate to the source of CCL2 and are frequently recruited to tumor tissue, where they differentiate into tumor-promoting TAMs." (PMID 31811337, 2020). "The expression of chemokines for CCR2 (Ccl2 and Ccl7) or CCR5 (Ccl3, Ccl4, and Ccl5) in tumor-bearing lungs, chemoattractants for monocytes/macrophages, was unchanged in FROUNT-cKO mice." (PMID 32001710, 2020). "We also probed for myeloid cells expressing CXCR3 (the receptor for CXCL9-11) and CCR2 (one of the receptors for CCL11 and uniquely a receptor for MCP1) within our tumor digests." (PMID 31940491, 2020). "Circulating monocytes can be recruited into the tumour by the CCL2-CCR2 axis and the blockade of CCR2 decreases monocyte recruitment, tumour growth and metastasis in an orthotropic model of PDAC." (PMID 32635552, 2020). "We further provided the evidence that HFD‐induced gut dysbiosis stimulated tumour cell proliferation and decreased apoptosis, modulated cytokines and chemokines by activating MCP‐1/CCR2 axis and ultimately promoted intestinal carcinogenesis." (PMID 31957197, 2020). "The most important function of CCL2 is the CCR2-mediated recruitment of TAM and MDSC into the tumor niche." (PMID 33182504, 2020). "Activation of CCR2 signaling prompts TAMs to secrete another chemokine, CCL3, leading to enhanced TAMs–tumor cell interaction and prolonged retention of TAMs in the metastases sites, which promotes extravasation of breast cancer cells." (PMID 33414786, 2020). "Transferred T cells showed a significant migration towards xenograft tumor in response to tumor-derived CCL2, whose transmigrate was directly mediated by CCR2 recognition." (PMID 32483450, 2020). "Phenotypic profiling revealed maximal expression of CCR2 by tumor-resident MDSCs, and MCP-1 by transplanted TC1 tumor cells, respectively." (PMID 33322474, 2020). "To address the mechanisms underlying the antitumor effects of celecoxib, we focused on the tumor microenvironment and examined the levels of chemokines CCL2 and CXCL10 and their receptors, CCR2 and CXCR3, respectively." (PMID 32943658, 2020). "Given its efficacy in blocking CCR2+ cell recruitment in the thioglycolate studies, we expected the compound would decrease MDSC numbers within tumor-bearing WT mice." (PMID 33322474, 2020). "We found comparable tumor volume and a similar quantity of Tim-4+ TAMs in mice receiving PBS and CCR2 antagonist." (PMID 32780724, 2020). "Whether ApB and Exo possessed tumor selectivity remained to be elucidate, although our current data strengthened that MiV directly budded and pinched off from the cell membrane and significantly enriched with CCR2, which allowed MiV to recognize tumor cells in response to chemokine gradient." (PMID 32550891, 2020). "In many cancers, tumor-associated macrophages (TAMs) are constantly recruited to the tumor environment by the CCL2 chemokine, which attracts CCR2+ monocytes circulating in the blood." (PMID 33153193, 2020). "The inhibition of the CCL2–CCR2 complex or CCL2 or CCR2 alone, has provided a lowering in tumor growth and prolonged survival in some cancers, giving another opportunity to evaluate a new cancer treatment." (PMID 33228048, 2020). "In contrast with previous studies, which targeted the CCR2/CCL2 pathway primarily in alternative experimental models, we found enhanced tumor volumes in Ccr2-/- mice." (PMID 32668709, 2020). "Combination therapy using a CCR2 antagonist (CCX872) and anti-PD-1 antibody to inhibit MDSC recruitment into the tumor microenvironment for KR158 (HGG-like cells) and 005GSC (stem-like cells) murine models increases IFNγ+TILs and prolongs overall survival." (PMID 32707672, 2020). "These processes occur by direct binding of given chemokine to a respective chemokine receptor, CCR2 and CXCR4, which are expressed by tumor vessels, or by promoting the recruitment of leukocytes." (PMID 32456359, 2020).
tumor (continued). "Most studies have shown that CCR2/CCR4 are highly expressed in tumors and promote tumor progression." (PMID 33318300, 2020). "It is worth noting that combined treatment with CCR2 inhibitors and CXCR2 inhibitors can overcome this compensatory effect, and augment anti-tumor immunity and improve response to FOLFIRINOX chemotherapy, prolonging the survival of PDAC mice." (PMID 33224886, 2020). "To further explore the function of tumor infiltrating macrophages in esophageal carcinogenesis, we constructed ESCC mouse model with CCL2 and CCR2 gene deletion." (PMID 32103760, 2020). "In agreement with our findings from pharmacologic inhibition of CCR2, we observed that CCR2KO mice had decreased anorexia during PDAC compared to WT tumor mice." (PMID 32391790, 2020). "CCL2 produced by murine GBM cells recruits CCR4+Tregs and CCR2+Ly-6C+ mMDSCs while MIF produced by tumor stem cells activates MDSCs, resulting in an immunosuppressive tumor microenvironment." (PMID 32707672, 2020). "We found that tumor cells release a chemokine, MCP-1, that attracts MDSCs as a result of their expression of the MCP-1 receptor, CCR2." (PMID 33322474, 2020). "The expression of CCR2, CXCR1, CXCR2 and CXCR4 are higher in human PCa tissues correlated with tumor aggressiveness." (PMID 32471499, 2020). "ZEB1 in TAMs, a TGF-β downstream transcription factor, induces the expression of CCR2, MMP9, and CCL2 in cancer cells to accelerate tumor growth." (PMID 33224886, 2020). "(c) Expression of CCR2, CCR4, CCR5, CCR7, CXCR1, CXCR2 and CXCR7 on tumor-infiltrating mast cells by gating on CD45+CD117+FcεRI+ cells." (PMID 30808413, 2019). "Work by Peng's group showed that tumor-derived fibroblasts secreted MCP-1 (known as CCL2), the ligand for CCR2 or CCR4, and RANTES (known as CCL5), the ligand for CCR1, CCR3, or CCR5." (PMID 30800130, 2019). "CSF-1R or CCR2 inhibition, in combination with chemotherapy, resulted in restored CD8+ T cells anti-tumor activity." (PMID 31878087, 2019). "Other stroma-targeted strategies include CSF-1R, CXCR1, CXCR2, and CCR2/CCR5 blockades, which inhibit the trafficking and recruitment of myeloid cells such as macrophages into the tumor." (PMID 31540435, 2019). "In HCC tissues, CCR2, CCR5 and their ligands are expressed by tumor as well as non-tumor cells and are modulated by inflammatory cytokines." (PMID 31377844, 2019). "Inhibition of CCR2 signaling blocks TAM recruitment and thus inhibits tumor cell seeding and persistent growth, improving the survival of mice." (PMID 30930117, 2019). "We have previously shown that HSC-derived DDR2+ cells home to tumor via the CCR2/MCP-1 axis and are capable of differentiating into fibroblasts in the local tumor environment." (PMID 31015794, 2019). "The CCR2+ inflammatory TAM subset accumulates at the highly vascularized HCC and has pro-angiogenic properties or tumor vascularization in fibrotic livers." (PMID 31572568, 2019). "CCR2-dependent TAM were shown to have a primary role in shaping the TME, thus promoting tumor expansion." (PMID 31417566, 2019). "Local radiation of tumor-bearing mice resulted in tumor cell production of the type 1 interferon IFNβ which, in turn, induced CCL2, CCL7, and CCL12 and chemoattracted CCR2+ M-MDSC to the tumor microenvironment." (PMID 31001479, 2019). "Pharmacological inhibition of CCR2 with a selective small molecule antagonist, CCX872, significantly suppressed tumor growth and enhanced survival in a spontaneous breast cancer model (HER2/neu transgenic mice)." (PMID 30800123, 2019). "CCR2 inhibitors and anti-CCL2 antibodies have shown efficacy in reducing tumor growth and metastasis in several pre-clinical murine models." (PMID 31878087, 2019). "The activation of chemokine receptor CCR2 in MSCs interacting with irradiated 4T1 cells was also observed, as well as higher expression of MCP-1/CCL2 in the tumor parenchyma of 4T1 mice." (PMID 29615915, 2018).
tumor (continued). "CCR2 and CCR5, in contrast, promoted tumor site infiltration only in a chemokine ligand dependent manner." (PMID 30319622, 2018). "The F4/80+ TAMs present in these tumours represented 10.8 ± 3.3% of all live tumoural cells and expressed FAP, alongside the macrophage/TAM markers CCR2, CD11b, CD14, MHCII, IL4-R and MMR, with a low expression of the dendritic cell marker CD11c." (PMID 30054470, 2018). "Tumor-bearing mice received adoptive cellular therapy and either GFP+HSCs, GFP+CCR2+HSCs, or GFP+CCR2−HSCs." (PMID 30333482, 2018). "The area under ROC curve was the highest for the combination of CCL2 and CCR2 with commonly accepted tumor marker, which indicates a possible clinical significance of plasma CCL2 and CCR2 measurements in the diagnosis of BC." (PMID 30151375, 2018). "Upon binding to its receptor CCR2, CCL7 plays a pivotal role in the recruitment of macrophages by tumor cell-derived exosome-educated MSCs." (PMID 29915688, 2018). "These tumor-specific T-cells were generated using splenocytes of GREAT mice and were co-transferred into tumor-bearing mice that received infusion of different stem and progenitor cell populations (Sca1+HSCs, cKit+HSCs, CD133+HSCs, CD38+HSCs, or CCR2+HSCs)." (PMID 30333482, 2018). "This cohort received either no vaccine, dendritic cell vaccine, or APCs isolated from the tumor microenvironment derived from GFP+HSCs, GFP+CCR2+HSC-derived cells, or GFP+CCR2−HSC-derived cells." (PMID 30333482, 2018). "It is thus likely that blockade of MAM-recruiting chemokine receptors such as CCR1, CCR2, CCR5 has minimum effects on the tumor infiltration of CD8+ T and NK cells, which is indispensable for immunotherapy efficacy." (PMID 30483271, 2018). "A macrophage-tropic chemokine, CCL2, was produced by breast cancer cells in lungs, to recruit circulating monocytes expressing CCR2, a specific receptor for CCL2, to the tumor sites." (PMID 30597969, 2018). "For example, CD123+ pDCs were found to selectively express CCR2, CMKLR1, and CXCR3, receptors known to be involved in DC maturation, trafficking and recruitment at tumor sites whereas XCR1 and CX3CR1, were selectively expressed by CD141+ mDCs and CD1c+ mDCs." (PMID 29795118, 2018). "DsRed+CCR2+HSCs and GFP+CCR2−HSCs were intravenously injected in equal amounts (5 × 105 cells) into tumor-bearing mice that received lymphodepletion with 5 Gy total body irradiation." (PMID 30333482, 2018). "These evidences further verify that CCL2/CCR2 signaling is involved in the tumor microenvironment, which explained why l-CDL decreased the volume of tumor and diminished angiogenesis, and alleviated the TCIP after sciatic nerve injury." (PMID 28587280, 2017). "Hypoxia exacerbates all the steps even CCR2 expression on macrophages and RAGE on IRISOE tumor cells." (PMID 29262555, 2017). "Chemokines in turn ultimately trigger inward migration of a large number of leukocyte sub-populations (LSPs) bearing CCR2 / CCR5 receptors that embed into the tumor, and further drive tumor aggression and stem cell survival." (PMID 28441391, 2017). "In addition to alleviating immunosuppression mediated by MDSC, further increases in CD8+/Treg ratio by adding anti-CCR2 to combined IR + cGAMP treatment, alleviating suppression of a different type, may be responsible for the superior anti-tumor immunity we observed." (PMID 29170400, 2017). "The proportion of CCR2+ cells was around 50% lower among both CD4+ and CD8+ T lymphocytes in tumor as compared with unaffected tissue." (PMID 29020986, 2017). "TNFα evoked release of tumor-promoting chemokines such as CCL2 (MCP-1), CCL5 (RANTES) and CXCL8 (IL-8) trigger infiltration of CCR2/CCR5 receptor bearing leukocyte sub-populations (LSPs) including TAMs, MDSCs, TANs, Tregs, MAMs and CAFs." (PMID 28441391, 2017).
tumor (continued). "In aggressive malignancies, metastatic MAMs arrive at secondary sites and in turn recruit inflammatory CCR2 bearing monocytes by CCL2, which in themselves release CCL3 and express CCR1, amplifying tumor potential." (PMID 28441391, 2017). "We performed Elispot assays for IFNγ secreting capacity of CD8+ T cells derived from the draining lymph nodes of tumor-bearing WT or CCR2−/− mice 7 days post-IR, using MC38 cancer cells as sources of tumor antigen." (PMID 29170400, 2017). "In accordance, the receptor of CCL2, CCR2, is required to facilitate increased MDSC presence and tumor growth." (PMID 28212753, 2017). "Treatment with anti-CCR2 antibody alleviates immunosuppression following activation of the STING pathway, enhancing the anti-tumor effects of STING agonists and radiotherapy." (PMID 29170400, 2017). "The altered expression of CCL2 and CCR2 was found in NSCLC cells and was correlated with sex, smoking habits, histology and tumor size." (PMID 28424406, 2017). "We have further specified this phenotype with the use of additional markers CCR2 and CX3CR1 which allowed us to define a specific population, induced in our tumor model and to give a hint towards possible immune regulation." (PMID 28744322, 2017). "Confocal microscopy of frozen lung sections from 4T1.2 tumor-bearing mice revealed increased intra- and extracellular S100A9 in areas of CCR2+CD115+ monocyte accumulation, thus confirming the in vivo imaging." (PMID 28744322, 2017). "Together suggest that at least in culture, CCL2 secreted by MSCs-entrained IRISOE TNBC tumor cells recruits THP1-macrophages to the vicinity of tumor cells, most likely through inducing expression of CCR2 on naïve THP1-macrophages surface." (PMID 29262555, 2017). "Double staining of lymph node sections for tumor cells and T cells (using anti-SV40 TAg and anti-GFP antibodies) identified that the CCR2-transduced T cells were in contact with tumor cells." (PMID 27177227, 2016). "Both CCR2 and CCL2 positively correlated with Fuhrman grade (P = 0.004 and P < 0.001, respectively) and presence of tumor necrosis (P < 0.001 and P = 0.021, respectively)." (PMID 27409666, 2016). "Chemotherapy promoting chemokine expression in tumor microenvironment affects leukocyte migration, such as CCL2/CCR2 pathway reboots antigen-specific T cell responses." (PMID 26459255, 2016). "Our previous study has identified that the main ligand for CCR2, CCL2, was highly expressed in gastric tumor tissues, and correlated with tumor progression." (PMID 26992207, 2016). "Here, we determine that both the CCL2:CCR2 and CCL5:CCR5 chemokine axes are uniquely modulated by RT in various tumor models." (PMID 27852031, 2016). "According to the cutoff value, 56.0% (150/269) and 63.8% (171/268) of the tumor tissues were scored as high CCL2 and high CCR2 expression, respectively." (PMID 27409666, 2016). "Animal studies have shown that host immunity can contribute to the anti-tumour activity of BRAF inhibition, with CCR2 suggested as an important participant." (PMID 26857260, 2016). "The initially secreted chemokines at the tumor site play a key role defining the composition of the tissue stroma and recruiting tumor infiltrating leukocytes bearing specific chemokine receptors (CXCR1, CXCR2, CCR2, CCR4, or CCR5, among others)." (PMID 25688243, 2015). "Expression of the inflammatory chemokine receptors, CCR1, CCR2, CCR3, CCR5 and CX3CR1, was significantly enriched on both Foxp3+ and Foxp3− CD4+ T cells within the tumours when compared with spleens and lymph nodes." (PMID 25495686, 2015). "MDSCs are recruited into tumors via the chemokine GPCRs CCR2, CXCR2, or CXCR4 and are believed to promote tumor progression, such as facilitating metastasis in CRC." (PMID 25110692, 2014). "NK cells migrate to lymph nodes mainly by utilizing CXCR3, while their migration to the inflamed tissues including tumor sites involves CCR1, CCR2, CCR5, CXCR3, and CX3CR1." (PMID 24966464, 2014).
tumor (continued). "Such tumor infiltrating monocytes/macrophages are recruited by CCL2 produced by L-MSCs and CCR2 expressed on TAMs." (PMID 25110692, 2014). "In breast cancer, CCR2/CCL2 interaction recruits macrophages into the lung, where the cells “create” an appropriate microenvironment to facilitate tumor cell lodging and the development of metastatic foci." (PMID 25110692, 2014). "This involves upregulated expression of CCR2 and CCL2 by tumor cells that increase the interaction between tumor and vascular ECs." (PMID 25110692, 2014). "In CCR2−/− mice, the accumulation of MDSCs is significantly reduced, indicating that MDSC infiltration in the tumor is dependent on the chemokine GPCR CCR2 and its ligands, mainly CCL2 produced in the tumor." (PMID 25110692, 2014). "CCL2 can also directly induce angiogenesis in endothelial cells, which express its receptor, CCR2, and induce VEGF and hypoxic-inducible factor (HIF)-1 in tumor cells." (PMID 23847541, 2013). "We investigated the distribution of CCR2 and CCL2 in T cells and tumor cell lines, respectively, established from specimens of additional CRC patients." (PMID 21450101, 2011). "We have also shown that migration is dependent on CCR2 expressed by T cells and CCL2 secreted by tumor cells." (PMID 21450101, 2011). "Because we have observed association of CCR2+ macrophage trafficking with tumor cell-produced hBD-3, but not MCP-1, in oral CIS lesions and in xenograft tumors in nude mice, we hypothesized that hBD-3 mediates monocyte/macrophage migration by acting through CCR2." (PMID 20544025, 2010). "CCR2 is a major receptor for the MCP-1 which is produced largely by tumour cells and is responsible for recruiting macrophages to tumours in bladder, cervix, ovary, lung and breast." (PMID 20537184, 2010). "Previous studies have found that using CCR2 inhibitors can significantly reverse the enrichment of macrophages in the tumor tissue, effectively reduce the tumor burden of CTCL, and thus, demonstrate good anti-tumor activity." (PMID 41614909, 2026). "Using the CCR2 antagonist RS504393 in our in vivo studies, we found that combining RS504393 with cisplatin significantly reduced tumor volume and mass in F. nucleatum-infected mice compared to cisplatin alone (P = 0.0011 and 0.0075), demonstrating the anti-resistance effect of CCR2 blockade." (PMID 41276817, 2025). "It will be of interest to monitor the tumor cell-directed approach (HER2) as opposed to the myeloid-directed approaches (CCR2 and salmonella) to gain greater insight into the cell type of relevance for therapeutic STING targeting." (PMID 39846804, 2025). "To reassess the role of Ccr2-mediated monocyte recruitment to lung metastasis, we analyzed the infiltration of Ly6Chi monocytic cells in the lungs of BL6, Ccr1-/- and Ccr2-/- mice, 12- and 24-h post-intravenous tumor cell injection." (PMID 39566333, 2025). "Recent research has also explored blocking the CCL2/CCR2 signaling axis, responsible for monocyte recruitment and M2 differentiation, as a promising strategy to reduce TAM infiltration in the TME and enhance anti-tumor immune responses." (PMID 40843751, 2025). "By simultaneously reducing CCR2 expression and MDSC populations, Roscovitine disrupts critical pathways involved in MDSC-mediated immune suppression, thereby promoting enhanced anti-tumor immunity when used in combination with ICB." (PMID 41561738, 2025). "The downregulation of CCR2 in CD8+CD57+ T cells may affect their migration to TME enriched with chemokines (such as CCL2), thus weakening the local anti-tumor response." (PMID 41194936, 2025). "The homing mechanism is facilitated by MSC surface expression of key chemokine receptors, including CXCR4 and CCR2, which detect and respond to chemotactic gradients established by tumor-secreted factors such as SDF-1, MCP-1, and CXCL12 within the tumor microenvironment." (PMID 41301162, 2025).